GDF9 (growth differentiation factor 9)
Diseases named in the same sentence as GDF9 in open-access papers (continued):
Sharing a sentence is not in itself a finding about the gene and the disease.
endometriosis (5 papers, 2018 to 2025). The growth of functional endometrial tissue in anatomic sites outside the uterine body. "An indication that aberrant GDF9 function may be associated with endometriosis arises from reports of lower concentrations of GDF9 protein and mRNA in follicular fluid of patients with severe endometriosis." (PMID 36380138, 2023). "A previous study reported a lower concentration of GDF9 in the follicular fluid of patients with severe endometriosis." (PMID 36380138, 2023). "Kawabe and colleagues also showed lower GDF9 mRNA expression in granulosa cells of patients with endometriosis compared to controls." (PMID 36380138, 2023). "Curcumin can target the TNF-α expression to improve the growth differentiation factor-9 (GDF-9) expression in peritoneal fluid of women with endometriosis." (PMID 32244563, 2020). "It is possible that GDF9/BMP15 may be aberrant in specific populations of women with endometriosis, such as has been reported for AMH relative to endometriomas." (PMID 36380138, 2023). "We previously reported abnormal GDF-9 and KitL expression in endometriosis." (PMID 31417983, 2018). "However, it is unknown if the presence of endometriosis affects serum GDF9 or BMP15." (PMID 36380138, 2023). "Next, we evaluated AMH, KL, and GDF-9 protein expression in the ovaries of rats with and without endometriosis." (PMID 40002761, 2025). "GDF9 and BMP15 as potential serum biomarkers of oocyte quantity/quality may therefore be altered in patients with endometriosis." (PMID 36380138, 2023). "The lack of significant changes in GDF-9 and KL protein expression in the ovary in vivo suggests that endometriosis may impair ovarian apoptosis and follicular development through alternative mechanisms." (PMID 40002761, 2025). "The aim was to evaluate the effects of curcumin on growth factors expression by evaluating Growth Differentiation Factor-9 (GDF-9), Kit Ligand (KitL), and Tumor Necrosis Factor α (TNFα) expressions in bovine cumulus-oocyte complexes (COC)s cultured with PF from infertile women with endometriosis." (PMID 31417983, 2018). "The dilutional effect on GDF9 and BMP15 in serum may be important given that their normal concentration is very low and undetectable in a large proportion of women, potentially affecting the lack difference in the biomarker concentrations detected in women with endometriosis and in controls." (PMID 36380138, 2023). "Endometriosis decreased AMH protein expression (p < 0.05 vs. Sham), although no significant changes were seen in KITLG (KL mRNA) or GDF-9 expression." (PMID 40002761, 2025). "For clinical application in reproductive medicine, GDF9 and BMP15 serum biomarker quantitation is unlikely to be aberrant in the presence of endometriosis." (PMID 36380138, 2023). "Together, these results do not demonstrate strong evidence of GDF9 and BMP15 being affected by the presence of endometriosis." (PMID 36380138, 2023). "However, until recently, there have not been assay methods available to reliably measure GDF9 or BMP15 in human sera and thus assess if concentrations are altered in patients with endometriosis." (PMID 36380138, 2023). "Therefore, for clinical application of GDF9 and BMP15 as potential serum biomarkers in reproductive medicine, quantitation in serum is unlikely to be aberrant due to the presence of endometriosis." (PMID 36380138, 2023). "This study aims to measure serum GDF9/BMP15 in patients with and without endometriosis, to assess whether concentrations are affected by the presence and/or stage of endometriosis, diagnosed by laparoscopic procedures." (PMID 36380138, 2023).
bladder cancer (4 papers, 2019 to 2025). "GDF2 suppresses breast and ovarian cancer metastasis, while GDF9 (up-regulated 3.75-fold by curcumin) exhibits tumor-suppressive effects in bladder cancer." (PMID 40430278, 2025). "Specifically, ectopic expression of GDF-9 in bladder cancer cell lines attenuated cell growth, and reduced migration and adhesion." (PMID 31842336, 2019). "Another member of bone morphogenetic proteins (BMPs), the growth differentiation factor-9 (GDF-9), was suggested as a possible tumor suppressor in bladder cancer." (PMID 31842336, 2019). "The study also suggested that GDF-9 expression, while clearly present in normal bladder tissue, was absent from bladder cancer tissue samples." (PMID 31842336, 2019).
breast carcinoma (4 papers, 2008 to 2022). "GDF9 (growth differentiation factor 9) has been shown to reduce the invasiveness of breast cancer cells." (PMID 18922183, 2008). "We constructed a novel 6-gene signature (SQSTM1, GDF9, LINC01125, PTGS2, GVINP1, and TMEM64) and used an XGBoost model to predict the metastatic status in breast cancer (AUC = 0.82)." (PMID 35436939, 2022). "In conclusion, our present research constructed a novel 6-gene signature (SQSTM1, GDF9, LINC01125, PTGS2, GVINP1, and TMEM64) by feature importance score and used an XGBoost model to predict the metastatic status in breast cancer (AUC = 0.82, higher than the previous studies to our knowledge)." (PMID 35436939, 2022). "We speculated whether these 5 genes, LINC01125, GDF9, PTGS2, GVINP1, and TMEM64, contributed to breast cancer metastasis because of immune dysfunction and conducted an exploration from the immune cell perspective." (PMID 35436939, 2022). "Although there is little evidence that myostatin or GDF-9 is expressed in breast cancer, inhibition of the BMP receptor, activin receptor-like kinase 2 (ALK2), can reduce metastatic spread of mammary tumors in mice." (PMID 28583174, 2017). "Researches on gene LINC01125, gene GDF9 and gene GVINP1 is very limited, no studies have shown that there is a link between gene TMEM64 and breast cancer." (PMID 35436939, 2022).
keloid (4 papers, 2018 to 2024). An irregularly shaped, elevated mark on the skin caused by deposits of excessive amounts of collagen during wound healing. "Although it is difficult to know which of the keloid therapeutic targets is the most promising, we recommend paying attention to GDF-9, which controls cell proliferation, in addition to TGF-β1, which controls ECM production." (PMID 38279232, 2024). "The overexpression of growth differentiation factor‐9 (GDF‐9) in keloids enhances the proliferation, migration and invasion of keloid fibroblasts due to the phosphorylation of Smad 2/3 proteins through activation of the MAPK pathway." (PMID 36756687, 2023). "We previously showed that silencing of the TGF-β family member GDF-9 in keloid-derived fibroblasts downregulated p-Smad2 and p-Smad3." (PMID 33628711, 2021). "In particular, AKR1B10, revealed to be a differentially overexpressed gene in keloids through the whole-genome microarray analysis of lesions and normal tissue, and GDF-9, discovered through analysis using a TGF-β superfamily signaling gene chip, are attractive therapeutic targets." (PMID 38279232, 2024). "Therefore, GDF-9 provides a therapeutic target to control the cellularity of keloids, especially by inhibiting the proliferation of KFs." (PMID 38279232, 2024).
sterility (4 papers, 2018 to 2023). "There are no report on the involvement of GDF9 in Crohn, but mutations in GDF9 can result in sterility and lower ovulation rate." (PMID 30497370, 2018). "Indeed, the effect on ovulation rate and sterility can be reproduced in sheep and cattle through adapted immunization regimens, neutralizing more or less BMP15 or GDF9, and confirms the crucial role of these two factors." (PMID 32316494, 2020). "Particularly, two landmark studies demonstrated that the absence of two oocyte-specific growth factors, GDF9 and BMP15, causes sterility (mouse:; sheep:)." (PMID 32316494, 2020).
cyst (3 papers, 2017 to 2022). A sac-like closed membranous structure that may be empty or contain fluid or amorphous material. "Indeed, the formation of multi-oocyte follicles, indicative of the presence of defects in cyst breakdown and oocyte assembly with pre-granulosa cells, has been observed in Bmp15-/- Gdf9+/- mice." (PMID 36249842, 2018). "Both GDF9 and BMP15, which are representative oocyte secretory factors, are important for cyst breakdown, follicular development, and oocyte maturation." (PMID 35898394, 2022).
Obesity (3 papers, 2020 to 2024). Accumulation of substantial excess body fat. "As obesity led to an increase in the number of atretic follicles, we wondered if this increase was induced by the abnormal expressions of the genes BMP4, GDF9, or LHX8 that play key roles during ovarian follicular development." (PMID 33282873, 2020). "Obesity can disrupt either the expression or the effect of GDF9 and BMP15 factors, leading to the absence of a correlation between AMH and FSH." (PMID 39457645, 2024). "Thus, the present study sought to determine the effects of obesity on the serum BMP15, GDF9, and kisspeptin concentrations in women of reproductive age." (PMID 37790202, 2023).
ovarian disorder (3 papers, 2016 to 2024). A disease involving the ovary. "In female hosts, FMT resulted in a marked reduction in NAM concentration in the blood, and ovarian disorders-including weight reduction, reduced follicle number (mainly PmF), and altered folliculogenesis dynamics-associated with the decrease in AMH, GDF9, BMP15, and MVH proteins." (PMID 38948060, 2024). "It was shown that abnormalities in GDF9 could lead to the development of human ovarian diseases." (PMID 36360303, 2022).
Premature ovarian insufficiency (3 papers, 2021 to 2025). Amenorrhea due to loss of ovarian function before the age of 40. "GDF-9 is a member of the TFG-β superfamily that functions in follicle maturation with genetic variants found in premature ovarian insufficiency (POI)." (PMID 40649914, 2025). "Kuntai capsule can improve the estrous cycle and ovarian coefficient of rats with premature ovarian insufficiency, maintain the number of resting and growing follicles, and up-regulate the protein expression of growth differentiation factor 9, light chain 3 A-II, and Beclin 1 of rats’ ovaries." (PMID 36743924, 2022).
autoimmune disorders (2 papers, 2014 to 2022). "After preliminary studies, we selected three proteins essential for gonad development as potential targets for induced autoimmunity: gonadal soma-derived factor (Gsdf), growth differentiation factor 9 (Gdf9), and lymphocyte antigen 75 (Cd205/Ly75)." (PMID 25436775, 2014).
breast tumor (2 papers, 2022 to 2023). "Low expression of GDF9 was observed in breast tumours which developed bone metastasis in both TCGA and E-MTAB-4003 cohorts, whilst increased GDF11 expression was seen in those primary tumours which developed bone metastasis." (PMID 37333824, 2023). "Reduced expression of GDF9 and DAND5 was observed in breast tumours which presented with distant metastasis (P<0.05)." (PMID 37333824, 2023). "To elucidate the biological functions of SQSTM1, GDF9, LINC01125, PTGS2, GVINP1, and TMEM64 in breast tumor cells, we knocked down the expression of the 6-gene signature using shRNA or the negative control in MCF-7 cell lines to assess cell proliferation, migration and invasion in vitro." (PMID 35436939, 2022).
fragile X syndrome (2 papers, 2019 to 2024). A genetic syndrome caused by mutations in the FMR1 gene which is responsible for the expression of the fragile X mental retardation 1 protein. "The fibroblasts from POI patients, including fragile X syndrome, abnormal karyotype (45, X; 45, X/46, XX; 45, XO and 47, XXX), and the gene mutation (FIGLA and GDF9) were reprogrammed to pluripotency status by retroviral transduction using defined factors." (PMID 31151408, 2019). "Here, we apply and improve on previous methods to establish human POI-iPSC lines using 4 inhibitor culture systems from 7 POI patients with a family history, including Fragile X syndrome, abnormal karyotype (45, X; 45, X/46, XX; 45, XO and 47, XXX), and the gene mutation (FIGLA and GDF9)." (PMID 31151408, 2019). "Herein, human POI-iPSCs with genotype of POI, including fragile X syndrome, abnormal karyotype (45, X; 45, X/46, XX; 45, XO and 47, XXX), and the gene mutation (FIGLA and GDF9), were generated using a lentiviral vector with four reprogramming factors under the 4i culture system." (PMID 31151408, 2019).
ovarian tumors (2 papers, 2013 to 2017). "In the current study, ovarian tumors developed in mice harboring TGFBR1CA and Gdf9-iCre." (PMID 29221447, 2017).
Primary amenorrhea (2 papers, 2020 to 2024). "The first homozygous 1-bp deletion in the GDF9 gene was identified in POI-16 with primary amenorrhea published as a case report." (PMID 33095795, 2020). "The heterozygous GDF9 variants may be associated with a less severe phenotype (i.e. POI with secondary amenorrhea) whereas biallelic variants may lead to a more severe phenotype, such as primary amenorrhea." (PMID 38649916, 2024).
prostate carcinoma (2 papers, 2023 to 2025). A carcinoma that arises from epithelial cells of the prostate gland. "Growth differentiation factor 9 (GDF-9) has been reported to promote the metastatic ability of prostate cancer cells by promoting the expression of FAK and paxillin through a Smad-dependent pathway." (PMID 37175948, 2023).
adenomyosis (1 paper, 2023). The growth of endometrial tissue inside the muscular wall of the uterine corpus. "The presence of other gynaecological pathogenesis, i.e. adenomyosis (n = 3), endosalpingiosis (n = 1) and leiomyomas (n = 9), did not affect the concentration of GDF9 and BMP15 (data not shown)." (PMID 36380138, 2023).
clear-cell renal cell carcinoma (1 paper, 2023). "Gdf9 expression is decreased in clear-cell renal cell carcinoma (CCRCC) which is linked to long-term survival of patients." (PMID 37398910, 2023).
endometrial atypical hyperplasia (1 paper, 2024). "To verify whether the GDF9 bi-allelic variant can cause endometrial atypical hyperplasia, we collected uteri from 34-36 weeks old mice." (PMID 38643161, 2024).
endometritis (1 paper, 2021). An acute or chronic, usually bacterial infectious process affecting the endometrium. "Although it is difficult to explain this finding, however we assume that the effect on GDF9, StAR, and FSHr expression is associated with clinical endometritis rather than the sub-clinical endometritis." (PMID 33969045, 2021).
Insulin resistance (1 paper, 2012). Increased resistance towards insulin, that is, diminished effectiveness of insulin in reducing blood glucose levels. "For instance, high LH levels and insulin resistance can cause the malfunction of follicular granulosa cells and the abnormal expression of GDF-9, both of which markedly reduce the quality of the embryos." (PMID 22518124, 2012).
intrahepatic cholangiocarcinoma (1 paper, 2023). A carcinoma that arises from the intrahepatic bile duct epithelium in any site of the intrahepatic biliary tree. "So, due to its regulation of Gdf9 expression in oocytes, CPEB3 is crucial for the growth of ovarian follicles and female fertility. hsa_circ_0050898, which was derived from the ACTN4 gene’s exons 1 to exons 20, was overexpressed in intrahepatic cholangiocarcinoma." (PMID 36827016, 2023).
Ovarian cyst (1 paper, 2016). The presence of one or more cysts of the ovary. "The increased level of GDF9 mRNA in the ovaries of animals treated with TT should be the main reason for the success of TT in removing ovarian cysts." (PMID 26928288, 2016).
ZIKV infection (1 paper, 2022). "In this study, we found that the significantly decreased mRNA levels of GDF-9, EPAB, and BMP-15 and unaltered AMH after ZIKV infection can impede follicular development to the antral stage." (PMID 34730391, 2022).
Zinc deficiency (1 paper, 2024). A deficiency of the essential metal Zinc; an essential cofactor for many enzymes. "The mRNA levels of Gdf9 and Bmp15 were down-regulated in zinc deficiency mice, whereas the expression levels of Sohlh and Nobox were remarkably up-regulated." (PMID 38807213, 2024).
tumor (8 papers, 2008 to 2025). "In general, the effects of SQSTM in tumor cells are assigned as a risk factor, while the effects of the other 5 genes (GDF9, LINC01125, PTGS2, GVINP1, and TMEM64) in immune cells are assigned as protective factors." (PMID 35436939, 2022). "In summary, we assigned the effects of SQSTM in tumor cells as a risk factor and the effects of other 5 genes (GDF9, LINC01125, PTGS2, GVINP1, and TMEM64) in immune cells as protective factors." (PMID 35436939, 2022). "Although this indicates that gdf9 is a potential tumour suppressor in CCRCC which can be used a potential target for tumour drug development, very few studies have looked at drugs which target the gene for therapeutic reasons nor have they indicated the relative level of gdf9 expression." (PMID 37398910, 2023). "GDF15 (P = 1.62E‐12), GDF11 (P = 1.38E‐2), GDF9 (P = 7.2811E‐3), and GDF3 (P = 4.95E‐6) were significantly up-regulated in primary tumor tissue (n = 415) compared with that in normal tissue (n = 34)." (PMID 40153751, 2025).
cancer (5 papers, 2019 to 2025). A tumor composed of atypical neoplastic, often pleomorphic cells that invade other tissues. "In humans, gdf9 was recently shown to be a regulator of the development and spread of certain cancer cells including those of the breast and kidney." (PMID 37398910, 2023). "Although GDF9 nuclear expression has been observed in normal and cancerous human renal tubular epithelial cells suggesting that intracellular redistribution of GDF9 may be involved in cancer progression, data concerning nuclear GDF9 expression are limited, and it needs further research." (PMID 35269923, 2022). "Cancer cells of growing ribociclib-resistant tumors used a diverse set of M2-like differentiation stimulating communication pathways as shown by a range of markers: CSF1, CLCF1, several FGFs (1/2/7/17/18/23), the TGF family member GDF9, interleukin 5/11/12, MADCAM1 and PLAU." (PMID 40032842, 2025).
genetic disorder (2 papers, 2021 to 2022). "The genetic disorder is a major cause of POI and there are about 1–4% of genetic defects in POI patients caused by Gdf9 mutation." (PMID 34930897, 2021).
GDF9 also shares sentences with these, for which no sentence is quoted: ovarian carcinoma (2 papers); Addison's disease (1); amenorrhea (1); autoimmune polyglandular syndrome (1); autoimmune thyroiditis (1); Azoospermia (1); B-cell lymphoma (1); colorectal cancer (1); endometrial cancer (1); follicular disorders (1); galactosemia (1); immune dysfunction (1); kidney cancer (1); leiomyoma (1); lung carcinoma (1); malnutrition (1); myasthenia gravis (1); oral cancer (1); systemic lupus erythematosus (1); Turner syndrome (1); vitiligo (1).